XRCC6P5 (X-ray repair cross complementing 6 pseudogene 5)
Gene: Processed pseudogene on chromosome X (99,719,364 to 99,721,158, reverse strand). Ensembl gene ENSG00000215070.
Diseases named in the same sentence as XRCC6P5 in open-access papers:
XRCC6P5 is named in the same sentence as 59 diseases in open-access papers, as found by Europe PMC text mining. Sharing a sentence is not in itself a finding about the gene and the disease.
XRCC6P5 shares sentences with these, for which no sentence is quoted: tumor (44 papers); cancer (34); glioblastoma (18); breast carcinoma (11); glioma (9); lung carcinoma (5); colon cancer (4); brain tumor (3); breast tumor (3); colorectal cancer (3); Fanconi anemia (3); melanoma (3); pancreatic cancer (3); prostate carcinoma (3); hepatocellular carcinoma (2); microcephaly (2); neurodegenerative disease (2); Alzheimer disease (1); amyotrophic lateral sclerosis (1); anemia (1); aplastic anemia (1); Ascites (1); atherosclerosis (1); bladder cancer (1); bladder tumors (1); cortical cataract (1); developmental delay (1); Ewing sarcoma (1); gastric cancer (1); genetic disease (1).
A further 29 diseases each share a sentence with XRCC6P5 in 1 paper.